TRPC6 (transient receptor potential cation channel subfamily C member 6)
Diseases named in the same sentence as TRPC6 in open-access papers (continued):
Sharing a sentence is not in itself a finding about the gene and the disease.
atherosclerosis (8 papers, 2012 to 2025). A disease characterized by the build-up of fatty material and calcium deposition in the arterial wall resulting in partial or complete occlusion of the arterial lumen. "TRPC1 expression in atheroma macrophages was associated with advanced atherosclerosis, whereas medial TRPC6 upregulation correlated with increased histamine-induced calcium transients and coronary contractility." (PMID 28756533, 2017). "miR-26a acts as a negative regulator of TRPC6, activation of which allows Ca2+ influx activating the mitochondrial apoptotic pathway associated with atherosclerosis." (PMID 26482920, 2016). "It was discovered that miR-26a-5p, involved in endothelial apoptosis, is downregulated in atherosclerosis and directly targets transient receptor potential cation channel subfamily C member 6 (TRPC6) in VEC." (PMID 40076710, 2025). "TRPC6 expression and histamine-induced active tension as well as TRPC1 expression and atherosclerosis associations were analyzed." (PMID 28756533, 2017). "In other words, derepression of TRPC6 due to miR-26a downregulation critically contributes to the endothelial apoptosis in the setting of atherosclerosis." (PMID 25801675, 2015). "Taken together, our study identified for the first time miR-26a as a novel anti-apoptotic miRNA, which is dysregulated in atherosclerosis and directly targets TRPC6 in vascular endothelial cells." (PMID 25801675, 2015). "Besides, the upregulation of the TRPC6 mRNA expression was observed in the monocytes of patients with type-2 DM that promotes atherosclerosis." (PMID 34326888, 2021). "One study found that miR-26a might exert an anti-apoptotic effect in endothelium by inhibiting TRPC6-induced calcium overload, and its expression was reduced in ApoE−/− mice with atherosclerosis induced by high-fat diet." (PMID 30285853, 2018).
gastric cancer (8 papers, 2011 to 2024). A primary or metastatic malignant neoplasm involving the stomach. "In gastric cancer cells, this inhibitor has demonstrated the ability to block endogenous TRPC6 channels, leading to cell cycle arrest in the G2/M phase and inhibiting cell growth." (PMID 38784033, 2024). "In gastric cancer, TRPC6 and TRPM7 have been shown to influence oncogenic processes through modulation of intracellular calcium levels, which is critical for tumor progression." (PMID 39768254, 2024). "TRPC6-mediated Ca2+ influx in gastric cancer cell lines is responsible for regulation of the cell cycle, as the inhibition of TRPC6 resulted in cell cycle arrest in the G2/M phase and inhibited cell growth." (PMID 32182937, 2020). "The TRPC6 channel was shown to be upregulated on protein and mRNA level in human gastric cancer epithelial cells in comparison to normal gastric epithelial cells." (PMID 32182937, 2020). "TRPC6, which can be activated both by receptor tyrosine kinases and GPCRs, appears to have a role in human esophageal and gastric cancer development." (PMID 21420431, 2011). "TRPC6 appears to have a role in cancer development, given that there is a marked upregulation of TRPC6 expression in esophageal squamous cell carcinoma and in epithelial cells of human gastric cancers." (PMID 21420431, 2011). "Blockade of TRPC1 and TRPC6 also holds considerable potential in GI oncology, given that TRPC1 may promote pancreatic cancer cell invasion and TRPC6 seems to play a significant role in human esophageal and gastric cancer development." (PMID 21420431, 2011). "Moreover, exploring whether TRPC6 antagonists can enhance the effectiveness of common gastric cancer chemotherapeutic agents, including paclitaxel and cisplatin, holds promise." (PMID 38370477, 2024). "In addition, the suppression of TRPC6 is known to inhibit gastric cancer formation." (PMID 33859522, 2021). "Recent studies have highlighted the role of transient receptor potential (TRP) ion channels, particularly TRPC6 and TRPM7, in the progression and metastasis of various cancers, including gastric cancer." (PMID 39768254, 2024). "It is worth noting that TRPC6 and TRPM7 ion channels are also known to play roles in gastric cancer progression." (PMID 39768254, 2024). "By integrating gene-silencing techniques targeting B7H6 with the potential regulatory effects on TRPC6 and TRPM7, we aim to explore a novel approach to overcoming drug resistance in gastric cancer therapy." (PMID 39768254, 2024). "Notably, six TRP channels (TRPC6, TRPM2, TRPM5, TRPM7, TRPV4, and TRPV6) have been identified as crucial players in the growth and survival of gastric cancer." (PMID 38370477, 2024).
membranous glomerulonephritis (8 papers, 2010 to 2023). A slowly progressive inflammation of the glomeruli characterized by immune complex deposits at the glomerular basement membrane, resulting in a thickened membrane, and nephrotic syndrome. "In addition to the effects of gain-of-function mutations in the TRPC6 gene, also elevated levels of wild-type TRPC6 protein in some acquired glomerular diseases, like membranous nephropathy and puromycin aminonucleoside-induced albuminuria, may lead to podocyte dysfunction." (PMID 22844592, 2012). "Several studies showed that TRPC6 expression is upregulated in various human proteinuric kidney diseases, such as minimal change disease (MCD), membranous glomerulonephritis (MGN), autoimmune glomerulonephritis, diabetic kidney disease (DKD), and FSGS." (PMID 37615749, 2023).
prostate carcinoma (8 papers, 2008 to 2024). A carcinoma that arises from epithelial cells of the prostate gland. "TRPC6 is detected in benign and malignant human prostate tumor tissues as well as in prostate cancer cell lines and its expression levels are associated with the histological grade." (PMID 29772843, 2018). "Abnormal ion channels, such as transient receptor potential canonical 6 (TRPC6), are reported to be involved in the carcinogenesis and progress of prostate cancer and have become potential drug targets against prostate cancer." (PMID 38567350, 2024). "This compound can effectively inhibit the growth of prostate cancer cells growth both in vitro and in vivo, demonstrating the therapeutic potential of TRPC6 antagonists in treating prostate cancer." (PMID 38567350, 2024). "In human prostate cancer epithelial (hPCE) cells, active TRPC6 and nuclear factor of activate T cells (NFAT) promote proliferation via alpha 1-adreniergic receptor signaling." (PMID 32138386, 2020). "Expression profiles of some TRP channels including TRPC6 are changing during the progression of prostate cancer towards the more aggressive and hormone-refractory stages." (PMID 29772843, 2018). "In prostate cancer, TRPC6 is suggested to be involved in cancer cell invasion into a “matrigel-based” matrix." (PMID 29772843, 2018). "Taken together, our study describes for the first time that PCC0208057, a novel TRPC6 inhibitor, might be a promising lead compound for treatment of prostate cancer." (PMID 38567350, 2024). "Moreover, the proliferation of PC-3 prostate cancer cells was decreased by silencing the expression of TRPC6." (PMID 32210800, 2020). "Studies have found that the expression of TRPC6 in prostate cancer cells is closely related to tumor stage and grade, suggesting that TRPC6 channels might be a novel anti-cancer drug target against prostate cancer." (PMID 38567350, 2024). "Molecular mechanism studies revealed that PCC0208057 could directly bind and inhibit the activity of TRPC6, which then induces the prostate cancer cells arrested in G2/M phase via enhancing the phosphorylation of Nuclear Factor of Activated T Cells (NFAT) and Cdc2." (PMID 38567350, 2024). "Here, we report a novel small molecule inhibitor of TRPC6, designated as PCC0208057, which can suppress the proliferation and migration of prostate cancer cells in vitro, and inhibit the formation of Human umbilical vein endothelial cells cell lumen." (PMID 38567350, 2024). "TRPC6 has been shown to make a complex with TRPC3 in neuronal cells and prostate cancer epithelial cells." (PMID 32138386, 2020). "Similar to TRPC6, TRPV6 channel upregulation in prostate cancer cells is known to represent a mechanism for maintaining a higher proliferation rate, increasing cell survival and apoptosis resistance." (PMID 31627357, 2019). "Moreover, TRPV6 is strongly expressed in advanced prostate cancer, with little or no expression in healthy and benign prostate tissues, and high TRPC6 expression has been documented in esophageal squamous cell carcinoma." (PMID 33076385, 2020). "At the same time, after TRPC6 gene was silenced by siRNA gene silencing, the expression of TRPC6 protein was decreased, and the inhibitory effect of PCC0208057 on the proliferation of prostate cancer cells was weakened compared with the non-silenced cells." (PMID 38567350, 2024). "The prostate cancer cell line (LNCaP) was used as a positive control for TRPC3 and a negative one for TRPC6." (PMID 18452628, 2008).
Anxiety (7 papers, 2021 to 2025). Intense feelings of nervousness, tension, or panic often arise in response to interpersonal stresses. "TRPC6 deficiency not only causes anxiety and depression but also reduces the excitability of the CA1 region in the hippocampus." (PMID 40076986, 2025). "TRPC6-deficient mice displayed anxiety- and depression-like behaviors, and hyperforin was shown to activate TRPC6 selectively, enhancing hippocampal excitability and synaptic plasticity." (PMID 41465351, 2025). "The anxiolytic and antidepressant effect of hyperforin was demonstrated by activating TRPC6 via a specific binding motif, which excited hippocampal neurons in mice and significantly reversed anxiety-like behavior in the OFT." (PMID 40076986, 2025). "We next compared the depression- and anxiety-like behaviors in these conditionally TRPC6-knockdown male mice (TRPC6-cKD) with that in the control mice (infected with a virus carrying the scrambled shRNA)." (PMID 39642080, 2024). "Taken together, these results suggest down-regulation of TRPC6 in the VTA DA neurons promotes the phenotypes of depression/anxiety of the mice in the CMUS." (PMID 39642080, 2024). "In order to identify a possible neuronal correlate for depression- and anxiety-like behavior in TRPC6 KO mice, we investigate DG and CA1 neuronal excitability in acute hippocampal slices from WT and KO mice using whole-cell current-clamp recordings." (PMID 36224261, 2022). "Recently published data suggest that viral knockdown of TRPC6 in the DG of mice has a disadvantageous effect on cognitive processes and anxiety-like behavior." (PMID 36224261, 2022). "In summary, we demonstrate the role of TRPC6 channels for depression and anxiety and provide evidence for TRPC6 channels as novel druggable targets for therapies in mood disorders." (PMID 36224261, 2022). "We report that TRPC6 KO mice show an enhanced depression- and anxiety-like behavior." (PMID 36224261, 2022). "TRPC6 KO mice showed enhanced anxiety-like responses in the open field and elevated plus maze test and displayed increased depression-like behavior in the forced swim test and in the sucrose preference test reflecting the animal’s capacity to experience hedonic pleasure." (PMID 36224261, 2022). "In order to test an involvement of TRPC6 in depression and anxiety, we use a TRPC6 KO mouse model." (PMID 36224261, 2022). "Similar to various rodent models and the TRPC6-based Drosophila model of ASD, Ssdp overexpressing flies, in our study also exhibited elevated anxiety in an open field arena." (PMID 37486945, 2023). "Furthermore, selective knockdown of TRPC6 in the mPFC-projecting VTA DA neurons (virus-retro carrying DIO-Trpc6-shRNA (TRPC6-rcKD) was injected into the mPFC of Slc6a3-Cre male mice) also conferred the mice with the depression- and anxiety-like behaviors." (PMID 39642080, 2024).
autoimmune glomerulonephritis (7 papers, 2020 to 2023). An autoimmune form of glomerulonephritis (disease). "Mutations in TRPC6 are associated with FSGS and upregulation of TRPC6 activity has been seen in several proteinuric kidney diseases including autoimmune glomerulonephritis." (PMID 32708597, 2020). "Since TRPC6 is regulated in part by angiotensin II, a significant amount of research is being done to investigate its role in modulating non-congenital glomerular diseases such as diabetic nephropathy and autoimmune glomerulonephritis." (PMID 32708597, 2020). "To date, we have observed a glomeruloprotective effect with TRPC6 inactivation in three different chronic disease models (chronic PAN nephrosis, anti-GBM autoimmune glomerulonephritis and aging)." (PMID 33918778, 2021).
depression (7 papers, 2021 to 2025). "Keeping in mind that altered cognition is one of the symptoms of major depression and major depression is one of the main risk factors for dementia, TRPC6 might be a link between these psychiatric diseases." (PMID 36224261, 2022). "Moreover, they suggest that selective pharmacological activation of TRPC6 might be a promising approach to correct the aberrant firing pattern of hippocampal neurons associated with depression-like behavior." (PMID 36224261, 2022). "Our study provides strong and convincing evidence that TRPC6 is a key regulator of the VTA DA neurons which are known to be a key player in depression states." (PMID 39642080, 2024). "These facts with the fact that TRPC6 activator hyperforin is an effective antidepressant in multiple depression models, and that hyperforin is the principal component of St." (PMID 39642080, 2024). "In the mice depression model induced by corticosterone, a long-lasting antidepressant-like activity was induced by hyperforin by directly activating TRPC6." (PMID 35875795, 2022). "TRPC6 channels are expressed in several brain areas relevant for depression such as the dentate gyrus, where channel expression is particularly prominent, as well as in cortical regions." (PMID 36224261, 2022). "In a rat depression model, impaired cognitive ability along with decreased hippocampal TRPC6 expression was observed." (PMID 35875795, 2022). "Importantly, male mice with CRS-induced depression also showed a significant downregulation of TRPC6 protein in the VTA (0.38±0.06 fold, N=10 for control and N=14 for CRS, Two-sample t-test, t=7.369, df = 22, 95% CI: –0.8006 to –0.4489, p<0.0001)." (PMID 39642080, 2024). "Also, in a CMUS rat model, TRPC6 expression was found to be downregulated in the hippocampus, and administration of the TRPC6 opener hyperforin was effective in alleviating depression-like behavior." (PMID 39642080, 2024). "We also tested if this down-regulation of TRPC6 protein could also be found in a similar but different model of depression." (PMID 39642080, 2024). "Interestingly, hyperforin improves learning and memory, and decreases the neurotoxicity of amyloid deposits in models of depression and AD that also show reduced TRPC6 expression." (PMID 35501408, 2022). "John’s wort used to treat mild to moderate depression activates TRPC6 channels." (PMID 34577594, 2021). "This current study suggests down-regulation of TRPC6 expression/function is involved in reduced VTA DA neuron firing and chronic stress-induced depression-like behavior of mice." (PMID 39642080, 2024). "TRPC6 is involved in the signaling of brain-derived neurotrophic factor (BDNF), which is a pathophysiologically relevant neuropeptide in depression and stress disorders." (PMID 34577594, 2021). "Until now, depression-related behavior was not investigated in TRPC6 KO mice." (PMID 36224261, 2022).
epilepsy (7 papers, 2017 to 2023). A brain disorder characterized by episodes of abnormally increased neuronal discharge resulting in transient episodes of sensory or motor neurological dysfunction, or psychic dysfunction. "A deeper understanding of TRPC6 in neuroprotective signaling pathways will be beneficial for understanding the impact of this channel, especially in the setting of epilepsy." (PMID 36902145, 2023). "TRPC6 holds unique consideration in epilepsy, as it was shown to be downregulated under chronic epileptic conditions in the rat model." (PMID 36902145, 2023). "Studies with animal models for epilepsy and Parkinson’s disease showed a reduction in microglial activated state after TRPC6 and kir 2.1 blockade." (PMID 30498192, 2018). "Therefore, TRPC6 will be an interesting and important therapeutic target for epilepsy." (PMID 29326557, 2017). "TRPC3 and TRPC6 have been suggested to play contrasting roles in excitoxicity in a seizure induction model of epilepsy, with TRPC3 upregulated and TRPC6 downregulated in the hippocampus after pilocarpine-induced seizure." (PMID 34489621, 2021). "Here we performed a 10 years follow-up clinical analysis of an ASD individual who carries a disruption in the TRPC6 gene, and report that he is still non-verbal and presented one episode of epilepsy." (PMID 35501408, 2022).
Hypoglycemia (7 papers, 2020 to 2024). A decreased concentration of glucose in the blood. "In summary, this study identifies TRPC6 as a previously unrecognized sensor in response to hypoglycemia in brain under diabetic condition." (PMID 33135341, 2020). "A study conducted in mice demonstrated that this protein is sensitive to low glucose concentrations and is hence repressed when exposed to recurrent moderate hypoglycemia, as opposed to higher glucose concentrations, which cause an increase in mRNA and protein expression levels of TRPC6." (PMID 37372995, 2023). "Recurrent moderate hypoglycemia is common in treated DM, and a study of streptozotocin-induced diabetic APP/PS1 mice indicated that recurrent hypoglycemia could promote AD via the damaged TRPC6/GLUT3 pathway." (PMID 37623897, 2023). "We show that insulin-evoked hypoglycemia is severely aggravated in mice lacking the cation channel proteins TRPC1, TRPC4, TRPC5, and TRPC6, which cannot be explained by alterations in glucagon or glucocorticoid action." (PMID 39375537, 2024). "Recurrent moderate hypoglycemia is not thought to significantly affect GLUT3 expression, but it does reduce GLUT3-mediated glucose uptake, thus impacting cellular respiration and enhancing mitochondrial dysfunction, which, by extension, inhibits TRPC6 expression." (PMID 37372995, 2023).
minimal change disease (7 papers, 2010 to 2023). "Functional mutations of TRPC6 have been identified as a cause of hereditary FSGS, and elevated expression of TRPC6 was found in several forms of acquired human proteinuric diseases, including minimal change disease, FSGS, and membranous GN." (PMID 29619864, 2018). "Herein, we add to this body of literature by reporting a novel TRPC6 mutation in a family with phenotypic heterogeneity ranging from asymptomatic minimal change disease to end-stage kidney disease (ESKD)." (PMID 23663351, 2013). "Herein, we report a novel, autosomal dominant TRPC6 mutation in a family with disease ranging from asymptomatic minimal change disease to end-stage kidney disease." (PMID 23663351, 2013).